TLR4 (toll like receptor 4)
Diseases named in the same sentence as TLR4 in open-access papers (continued):
Sharing a sentence is not in itself a finding about the gene and the disease.
Stroke (continued). "It is likely that activation of TLR4 by host-derived ligands can also impact on stroke outcome as TLR4-deficient mice are protected against the ischaemic injury." (PMID 22114895, 2011). "Mice deficient in TLR4 have better outcomes following experimental stroke and decreased inflammatory responses, and the presence of TLR-4 on monocytes in stroke patients correlated to the extent of ischemic brain injury." (PMID 21385378, 2011). "Tlr4 is frequently implicated in stroke and initiates the downstream Myd88-dependent pathway." (PMID 39062789, 2024). "TLR4 deficient mice are protected from I/R injury in stroke." (PMID 39582054, 2024). "TLR4 expression is associated with infarct volume, stroke severity, and functional outcome." (PMID 37452512, 2023). "TLR4 activation is positively correlated with cerebral infarct volume, which may underlie the association of TLR4 expression with worse prognosis after stroke." (PMID 35419168, 2022). "However, we have recently described that TLR4 absence increases the levels of alternative neutrophils (N2), an effect associated with neuroprotection after stroke." (PMID 34745132, 2021). "It is known that TLR4 is implicated in brain damage and inflammation after stroke and that TLR4 absence induces neutrophil reprogramming toward a protective phenotype in brain ischemia, but the mechanisms remain unknown." (PMID 34745132, 2021). "TLR-4-deficient mice showed reduced infarct size, better outcomes in neurological and behavioral tests, and decreased level of inflammatory mediators following experimental stroke." (PMID 28115020, 2017). "Besides TLR2, TLR4 is also highly induced after cerebral ischemia, TLR4 deficient mice were protected against ischemic stroke, and polymorphisms of the TLR4 gene were found to be associated with stroke occurrence in a Chinese population." (PMID 26849209, 2016). "Even though stimulation of some PRRs (such as the TLR4), and the subsequent production of pro-inflammatory cytokines has been linked to increased infarct size and worse clinical outcome in stroke patients, the role of NF-κB activation as a consequence of stroke remains controversial." (PMID 26690125, 2015). "Clinical study showed that the level of TLR2 and TLR4 in neutrophils at 72 h and 7 days following ischemia and reperfusion was an independent indicator associated with the volume of brain infarction and prognosis of stroke patients." (PMID 23864765, 2013). "Interestingly, animals deficient in TLR2 or TLR4 have significantly reduced infarct sizes in several models of stroke." (PMID 21999375, 2011). "In addition, a recent investigation in humans showed that the inflammatory responses to stroke in the blood were linked to increased TLR2 and TLR4 expression on hematopoetic cells and associated with worse outcome in stroke." (PMID 21999375, 2011). "Additionally, iTBS may protect against motor deficits and neuronal damage caused by stroke by inhibiting the TLR4/NF-κB/NLRP3 signaling pathway, thereby regulating the M1/M2 phenotype balance in microglia." (PMID 39719979, 2024). "Furthermore, TLR4 is implicated in post-stroke inflammation." (PMID 38299364, 2024). "It has also been found that the loss of TLR4 in neutrophils regulates the induction of several pathways previously associated with inflammatory processes after ischemia, all of which may be the basis of neurological outcome during stroke." (PMID 34335600, 2021). "In addition to the deleterious effects, Gal-3 has been suggested as a target for the treatment of post-stroke gastrointestinal complications, as it is released after stroke and triggers central and peripheral enteric neuronal loss through a TLR4-mediated mechanism involving TAK1 and AMPK." (PMID 30258354, 2018). "These TLR4-independent mechanisms collectively exacerbate oxidative damage in post-stroke neurodegeneration." (PMID 40723833, 2025).
Stroke (continued). "Recent studies suggested that TLR4 exacerbates stroke prognosis in a rodent stroke model with middle cerebral artery occlusion (MCAO)." (PMID 40867143, 2025). "Atorvastatin significantly attenuated ischemia-induced overexpression of HMGB1, RAGE, TLR4, and NF-κB, significantly improving neurological deficits and reducing cerebral edema and infarct size 24 h after stroke." (PMID 38740617, 2025). "γδ T cells mediate post-stroke immunoinflammation through the TLR4/IL-17 axis, with their synergy with αβ T cells and interspecies heterogeneity presenting both therapeutic opportunities and challenges." (PMID 40746532, 2025). "The presence of MD2 is essential for the activation of TLR4 and the detection of DAMPs, underscoring the importance of this complex in the pathogenesis of stroke-induced neuroinflammation." (PMID 40723833, 2025). "In our study, an increased expression of HMGB1, TLR4 and NF-κβ1 was observed in the subacute phase, one week after the onset of stroke." (PMID 40332314, 2025). "MANF inhibited inflammatory responses and improved blood-brain barrier integrity after stroke in aged mice via the TLR4/MyD88/NF-κB pathway." (PMID 40919080, 2025). "The crucial role of TLR4 in the pathogenesis of stroke has been demonstrated, especially among microglia." (PMID 40289983, 2025). "Given the observed changes in its expression and correlation with Tlr4, it is likely that age-related epigenetic mechanisms contribute to the altered regulation of inflammatory responses in stroke." (PMID 40867143, 2025). "Toll-like receptor 4 (TLR4) has emerged as one of the central players in driving post-stroke inflammation." (PMID 40723833, 2025). "Conversely, PD-1 signaling, a major pathway protecting against CNS inflammation in MCAO, likely plays a crucial role in reducing stroke-associated TLR2- and TLR4-mediated neurotoxic factor release by activated CNS microglia." (PMID 40536592, 2025). "A chronic high-fat diet was found to exacerbate pyroptosis and necroptosis and worsen ischemic brain pathology by enhancing the HMGB1/TLR4/NF-κB signaling pathway after cerebral ischemia–reperfusion injury and leading to poor outcomes after stroke." (PMID 38740617, 2025). "TLR4-mediated neuroinflammation plays a key role in the pathogenesis of secondary sleep disorders after stroke." (PMID 38671959, 2024). "Conversely, research also reveals PRDX1’s damaging role in ischemic–reperfusion injury, promoting neuroinflammatory damage through the TLR4/NF-κB pathway and exacerbating stroke outcomes." (PMID 39595569, 2024). "TLR4-mediated neuroinflammation is pivotal in secondary sleep disorder pathogenesis following a stroke." (PMID 38671959, 2024). "Activating TLR4 initiates the NF-κB pathway and NLRP3 inflammasome, causing a subsequent increase in the pro-inflammatory cytokine IL-1β, closely tied to post-stroke sleep disturbances." (PMID 38671959, 2024). "TREM1 and TLR4 synergistically interact to enhance inflammatory responses, and co-activation is crucial for understanding the pathophysiology of stroke and potential therapeutic interventions." (PMID 38468280, 2024). "TLR4 has been identified as a potential target for stroke treatment because of its ability to bind circulating immune cells and activate an inflammatory response." (PMID 38049739, 2023). "Toll-like receptor 4 (TLR4) blockage also transforms neutrophils to an N2 phenotype after stroke, mitigating cerebral ischemic injury." (PMID 35906328, 2023). "We subsequently examined the expression of phospho-NF-κB p65 (p-p65), the downstream responder of TLR4, in foamy microglia after stroke." (PMID 37450211, 2023). "The inflammatory response after stroke is mediated by different signals, and one of these is represented by Toll-like Receptor 4 (TLR4)." (PMID 36671691, 2023). "Recent studies demonstrated that TLR4 has an important role in mediating inflammation and autophagy in many CNS diseases, such as stroke and sclerosis." (PMID 36879557, 2023).
Stroke (continued). "In T2DM mice, stroke induced earlier and higher TLR4, NLRP3, and cytokine expression (SAA, IL1β, IL6, TNFα) in the liver compared to heart and kidney, as measured by Western blot." (PMID 36968490, 2023). "In patients with AIS, elevated TLR4 levels in circulating monocytes correlate with increased stroke severity and cytokine levels." (PMID 37452512, 2023). "TLR4 mediates the activation of innate responses in monocytes, such as NF-κB activity and TNF-α synthesis, and are associated with worse outcomes in stroke patients." (PMID 34711943, 2022). "TLR4 is highly expressed in microglia and TLR4-dependent microglial activation has been described on neurodegenerative diseases like AD or after stroke." (PMID 35283778, 2022). "Platelets were identified as the main source of NET-inducing HMGB1 in stroke patients, and another group demonstrated, that murine platelets promote arterial thrombosis via TLR4-dependent NETosis induction." (PMID 35979369, 2022). "In a mouse model of photothrombotic stroke, producing a platelet-rich fibrin-free clot, administration of DNase I or Cl-amidine (targeting PAD4), as well as TLR4-deficiency in platelets completely reversed and inhibited thrombus formation, respectively." (PMID 35979369, 2022). "At the same time, vagus nerve stimulation down-regulated Toll-like receptor 4 (TLR4) expression in microglia in the acute phase of stroke and promoted microglia polarization to the M2 phenotype." (PMID 36569198, 2022). "We observed marked differences between WT and CD36 KO of multiple well-described inflammatory players in neonatal stroke and hypoxia–ischemia, including down-regulation of Tlr4, Timp1, Csf-1 and CD68." (PMID 35148760, 2022). "TLR4/NF-κB signaling pathway was connected with cellular processes in neurons and activated secondary inflammation in strokes." (PMID 35966335, 2022). "The TLR4 gene encodes a member of the Toll-like receptor (TLR) family of proteins, which show increased expression during stroke through multiple pathways." (PMID 36506580, 2022). "The anti-inflammatory impact of TLR4-inhibition in experimental stroke was specifically established by the administration of TLR4 blocking antibody (mAbs clone MTS510) in vivo." (PMID 36678774, 2022). "The TLR4 signalling pathway is one of the main immune mechanisms that enhances inflammation-mediated brain injury after stroke." (PMID 35419168, 2022). "The release of LPS, endotoxin found on the outer membrane of gram negative bacteria, activates an innate immune response by binding Toll-like Receptor 4 (TLR4) and is linked to exacerbating brain injury, stroke development and neuroinflammation." (PMID 36188471, 2022). "Overall, these data support that platelet TLR4 has a crucial role in stroke damage in a NET-dependent manner." (PMID 35250974, 2022). "MD2 is an essential cofactor protein of TLR4 that participates in the inflammatory response and is a key mediator of apoptosis and necroptosis in stroke models." (PMID 36016572, 2022). "Knowing that TLR4 is one of common CD36 co-receptor partners during inflammation and cerebral ischemia, including neonatal stroke, we measured protein levels of TLR4 in the ipsilateral and contralateral CPs of WT and CD36 KO mice." (PMID 35148760, 2022). "Stroke mice receiving PSCI-associated gut microbiota exhibited intestinal disruption and higher protein expression of TLR4, a receptor that recognizes LPS." (PMID 35379265, 2022). "The present study aims to investigate short-term add-on efficacy and mechanism of Panax notoginseng (Sanqi) for aspirin resistance in secondary stroke prevention via TLR4/MyD88/NF-κB signaling pathway." (PMID 36550905, 2022). "A previous study investigated the key role of TLR4 in the programming of N1/N2 neutrophils after stroke." (PMID 36091114, 2022). "Among TLR families, TLR2 and TLR4 are most studied which are closely relevant to the stroke-induced inflammatory response." (PMID 35185744, 2021).
Stroke (continued). "In order to assess the role of TLR4 on neutrophil function after stroke, TLR4loxP/loxP and TLR4loxP/Lyz-cre mice were subjected to pMCAO." (PMID 34745132, 2021). "We among others have been long dedicated to deciphering the role of TLR4 in the pathophysiology of stroke." (PMID 34745132, 2021). "In conclusion, using loss-of-function approaches, we demonstrated that neutrophil TLR4 is involved in neutrophil dynamics under physiological conditions as well as in stroke-induced brain damage." (PMID 34745132, 2021). "In contrast to the brain, stroke markedly increased expression of inflammatory-related factors, including IL-17a, TNFα, and TLR4, in the gut; however, IL-1β and MCP-1 levels were not increased as in the brain." (PMID 34327147, 2021). "TLR4 is specifically involved in neutrophil dynamics under physiological conditions as well as in stroke-induced tissue damage." (PMID 34745132, 2021). "Proteins of the peroxiredoxin family are released into the extracellular space 12–24 h after the onset of stroke, and Prx-5 and Prx-6 are able to activate macrophages through the TLR4-dependent signaling cascade." (PMID 34445509, 2021). "The impact of SNPs in CD14 (rs2569190), NF-κΒ (rs28362491), TLR2 (rs5743708), and TLR4 (rs4986790) on the incidence of combined endpoint defined as CV death, death from stroke, MI, and stroke/TIA was evaluated." (PMID 34305452, 2021). "Toll-like receptor 4 (TLR4) appears to be a key modulator of neutrophil polarization in the CNS, with specific myeloid ablation of TLR4 skewing neutrophils towards a neuroprotective phenotype following stroke that correlates with a reduced infarct volume." (PMID 35221216, 2021). "The protein–protein interaction of DJ-1 with TLR2 or TLR4 in infiltrating myeloid cells was successfully detected in the ischemic brain on day 1 after stroke onset." (PMID 34014921, 2021). "First, in patients with ischemic stroke, TLR4 expression on monocytes increases and correlates with circulating inflammatory mediators and stroke severity." (PMID 33903586, 2021). "Specifically, candesartan converts microglia to the M2 phenotype, which reduces stroke-induced neuronal injury by inhibiting TLR4 expression, IKBα and p65 phosphorylation, and NF-κB/p65 nuclear translocation in a TLR4/NF-κB dependent mechanism." (PMID 34594188, 2021). "Liu and his research team found that the NLRP3 inflammasome inhibitor provides a neuroprotection effect in stroke through TLR4/NF-κB/NLRP3 signaling pathway." (PMID 32908485, 2020). "Following stroke, the TLR4 signaling pathway is involved in the initial steps of neuroinflammation cascades, which result in brain injury such as vasogenic and cytotoxic edema and blood-brain barrier (BBB) disruption." (PMID 33552066, 2020). "A number of studies revealed that TLR4 plays a significant role in initiating the inflammatory response after stroke or TBI." (PMID 33613176, 2020). "This is consistent with current evidence demonstrating HMGB1 mediated microglial activation via the HMGB1/TLR4/NFkB axis in several disease contexts, including Parkinson’s disease, stroke, and epilepsy." (PMID 33096930, 2020). "Extracellular HMGB1 activates multiple membrane receptors, including but not limited to receptor for advanced glycation end products, and TLR4, through which it contributes to the pathogenesis of lung injury, stroke, cancer, and so on." (PMID 31798456, 2019). "HMGB1 was reported to bind to RAGE or activate the TLR4/MyD88 pathway, both of which promote the reduction of mature monocytes and lymphocytes in the circulation, and lead to subsequent post-stroke immunosuppression." (PMID 31001089, 2019). "Western blot analysis showed that TLR-4 and phosphorylated NF-κB (p-NF-κB) were elevated at 3 days after stroke in penumbra region, and their elevations were significantly inhibited by meisoindigo (P < 0.05)." (PMID 31920554, 2019).
Stroke (continued). "By blocking the TLR4 receptor, the extent of brain tissue edema, infarct size, and increased neurological damage scores after stroke are reduced in vivo, which possibly occurs via the TLR4/MyD88 signal pathway." (PMID 31001089, 2019). "In T1DM stroke rats, suppressing NFκB signaling pathway significantly decreases inflammatory factors such as RAGE and TLR4 expression in the ischemic brain and improves stroke outcome." (PMID 29896433, 2018). "In summary, our results showed that Gap19 exerted a neuroprotective effect after stroke via inhibition of the TLR4-mediated signaling pathway." (PMID 30386214, 2018). "TLR4 that is involved in pivotal processes, as inflammation and immunity, has been shown to mediate brain damage after stroke." (PMID 30384431, 2018). "This work confirms increased Prx6 expression in ischemic brain and the activation of stroke-induced TLR4 signaling, including enhanced TLR4 expression and NFκB activation." (PMID 30584250, 2018). "Consistent with immunostaining, Western blot assay show that D-4F treatment of T1DM stroke rats decreases TLR4, and nuclear NFκB expression in the ischemic brain compared to PBS treated T1DM stroke control rats." (PMID 29221142, 2017). "The results from western blot analysis on brain cortex tissues demonstrated the curative functions of TLR4/NF-κB and Nrf2/HO-1 signaling pathways in the protection against stroke with Danshensu and HSYA used separately and in combination." (PMID 29383171, 2017). "Both pharmacological inhibition of TLR4 and TLR4 knock-out in mice induce neuroprotection in experimental stroke." (PMID 28473983, 2017). "TLR-2 and the TLR-4 mutant mice showed significantly smaller post-stroke brain damage and lower neurological impairments compared with wild-type mice." (PMID 28115020, 2017). "We found in the current hyperglycemic stroke experiment that pregabalin has potent anti-inflammatory properties via downregulation of the HMGB1/TLR-4 signaling pathway and attenuation of p-NF-κB expression." (PMID 28152042, 2017). "We conclude that blocking TLR4 by the use of specific mAb is a promising strategy for stroke therapy." (PMID 26849209, 2016). "Previous studies from our laboratory have demonstrated protective effect in reducing acute inflammation in stroke model in TLR4 knockout mice in brain and optic nerve." (PMID 27314018, 2016). "Reactive oxygen species (ROS), nitric oxide (NO), and inflammatory cytokines produced by TLR4 activation play harmful roles in neuronal damage after stroke." (PMID 27143001, 2016). "Toll-like receptor 4 (TLR4) plays a pivotal role in the pathophysiology of stroke-induced inflammation." (PMID 27143001, 2016). "NOX4 has been shown to be upregulated and co-localized with TLR4, after cerebral ischemia and reperfusion in mice and in brain tissue of human stroke patients." (PMID 26030867, 2015). "Unexpectedly, recent studies suggest that activation of TLR4 is an important aspect of microglial phagocytosis and correlates with increased neurogenesis after stroke." (PMID 26690125, 2015). "SP-D is known to bind TLR2 and TLR4, as well as SHPS-1/SIRPα that are all expressed on and linked to induction of TNF in microglia and macrophages and involved in stroke." (PMID 25038795, 2014). "Dysregulation of TLR4 signaling appears to be involved in several disorders, including cerebral ischemia and stroke." (PMID 23690990, 2013). "LPS preconditioning redirects TLR4 signaling in response to stroke through suppression of NFκB activity, enhanced IRF3 activity, and increased anti-inflammatory/type I IFN gene expression." (PMID 21999375, 2011). "From the data of correlation analysis, they further found that TLR4 and serum cytokine expression levels were closely related to the severity of stroke." (PMID 20618938, 2010).